IL6 (interleukin 6)
Diseases named in the same sentence as IL6 in open-access papers (continued):
Sharing a sentence is not in itself a finding about the gene and the disease.
Obesity (continued). "According to the reported literature, adipocytes produced inflammatory cytokines such as IL-6 in obesity individuals." (PMID 35924148, 2022). "Obesity directly drives adipocyte cells towards inflammatory phenotypes, releasing pro-inflammatory cytokines, such as leptin, IL-6, IL-10, TNF-α." (PMID 35069893, 2022). "The circulating concentrations of inflammation related to obesity (leptin and adiponectin) and (IL-6 and IL-10)-related biomarkers were also analyzed in this study." (PMID 35207221, 2022). "Strikingly, myocytes also release excessive amounts of inflammatory cytokines (IL-6, IL-8, IL-15) and myokines in obesity thus leading to additional inflammation, damage to skeletal muscle cells, and disrupting endocrine activity." (PMID 36406206, 2022). "High fat diet caused metabolic, chronic, low-grade inflammation in the body because it induced obesity and the release of adipokines and inflammatory factors (For example, IL-1, IL-6, and TNF-α)." (PMID 37431015, 2022). "Between patients with obesity and stable plaques and with obesity and unstable plaques, differences were obtained for C-peptide (p = 0.046), TNFa (p = 0.0042), and the trend for IL-6 (0.05)." (PMID 36013196, 2022). "IL-6 also promoted tumor progression via STAT3 signaling in an obesity-induced liver tumor mouse model." (PMID 35205631, 2022). "In mice, a high-fat diet or genetic susceptibility and obesity promoted CRC development by increasing bile acid levels, which led to intestinal barrier impairment and enhanced IL-6/STAT3-related inflammation." (PMID 35154445, 2022). "Nonetheless, future studies are warranted to investigate alternative mechanisms linking obesity and poor PF, in particular the mediating roles of IL-6 and TNF-α." (PMID 35301057, 2022). "These events appear to affect myokines that are effective in sarcopenic obesity such as IL-6, IL-10, IL-15, myostatin, insulin-like growth factor (IGF-1), irisin, and fibroblast growth factor-21 (FGF-21)." (PMID 35250869, 2022). "Under inflammatory conditions, such as obesity and aging, the increase in IL-6 levels is accompanied by higher levels of TNF-α and its receptors, which are responsible for inducing pro-apoptotic responses." (PMID 36139762, 2022). "During obesity, neutrophils have high neutrophil elastase, neutrophil alkaline phosphatase, myeloperoxidase, IL-6, IL-1β, IL-12, IL-8, and TNF-α, and low expression of IL-10, which favors activation of M1 macrophages and development of chronic inflammation." (PMID 36230963, 2022). "It was shown that the concentration of CRP in the blood is higher in people (prepubertal and adults subjects) with overweight and obesity in relation to people with normal weight, possibly as a result of the production of IL-6 and TNF-alpha by adipose tissue." (PMID 35053667, 2022). "Previous studies have indicated that the plasma concentrations of proinflammatory cytokines, such as TNF α, and IL6 are elevated under conditions of insulin resistance in obesity and type 2 diabetes (Dandona, Aljada & Bandyopadhyay, 2004)." (PMID 36213511, 2022). "In the exercise scenario, despite the presence of obesity, in both mice and humans, increased IL-6 levels potentially enhance insulin and glucagon-like peptide-1 (GLP-1) secretion, improving glucose tolerance and insulin sensitivity." (PMID 36452038, 2022). "Evidence suggests that the elevations in pro-inflammatory cytokines observed in obesity, including interleukin 6 (IL-6), tumor necrosis factor-alpha (TNF-α), monocyte chemoattractant protein-1 (MCP-1), and serum amyloid, can be reduced via weight loss." (PMID 35350649, 2022). "Growing evidence indicates that the innate immune response pathway from the NLRP3 inflammasome, to interleukin-1 to interleukin-6, is involved in the generation of obesity-related systemic inflammation and heart failure with preserved ejection fraction." (PMID 36483560, 2022).
Obesity (continued). "Vice versa, in patients affected by obesity, macrophages undergo a polarization shift to a pro-inflammatory M1 phenotype and start expressing pro-inflammatory cytokines such as IL-6, TNF-α, MCP-1, etc." (PMID 36432422, 2022). "Inflammation is an important obesity-related disorder, and to verify the preventive effect of RB on this condition in a HSF-induced obesity model, we evaluated the pro-inflammatory cytokines, as IL-6 and TNF-α, in the heart tissue." (PMID 34636986, 2022). "Because we were focusing on inflammatory cytokines that play a major role in developing obesity, we quantified the level of IL-1β, IL-6, IL-17A, IFN-γ and TNF-α in the plasma of lean, HFD and GaELNs treated HFD mice." (PMID 35154484, 2022). "The most commonly studied cytokine in the studies included in this review is interleukin 6 (IL‐6), with some studies reporting higher IL‐6 levels in patients with obesity." (PMID 35837843, 2022). "The obesity- and inflammation-related gene (IL-6, TNF-α, IGF-1, leptin, AP2/FABP4, AMPK-α2, β3AR, and PPAR-γ) expressions in the liver and epididymal adipose tissue were reduced in the PHPB-treated group." (PMID 35386305, 2022). "The obesity due to the HSF diet caused cardiac inflammation, observed by elevated IL-6 and TNF-α cytokine." (PMID 34636986, 2022). "Obesity was also a kind of low-grade chronic inflammatory response, with increasing circulating levels of inflammatory cytokines, such as TNFα and IL6." (PMID 36145203, 2022). "Several pronociceptive and antinociceptive pathways have suggested to have an important role in the relation between obesity and pain sensitivity, particularly the presence of inflammatory markers such as interleukin-6 (IL-6) and C-reactive protein (CRP)." (PMID 35743474, 2022). "A systematic survey of obesity-related biomarkers showed that IL-6 and adiponectin are potential biological mediators linking obesity and asthma in children." (PMID 36253437, 2022). "As an important indicator, IL-6 has been widely used in experiments to study the influence of obesity on iron metabolism, and it’s generally believed that IL-6 takes a part in iron metabolism by regulating the expression of hepcidin in obesity." (PMID 36335331, 2022). "Studies have shown increased expression of inflammatory markers (i.e., TNF-α, IL-1β, and IL-6) by adipose tissue in mice with HFD-induced obesity." (PMID 35456900, 2022). "Obesity in childhood induces the secretion of adipocytokines such as leptin, TNF-α, and IL-6, and slows the secretion of adiponectin, which causes insulin resistance." (PMID 35742443, 2022). "Obesity, as a component of MS, is associated with chronic inflammatory state due to the production of proinflammatory cytokines, such as TNF-α and IL-6." (PMID 35223684, 2022). "On the other hand, obesity is characterized by a pro-inflammatory state with increased outflow of inflammatory cytokines (i.e., IL-6 and tumor necrosis factor-alpha)." (PMID 35334962, 2022). "Logistic analysis after adjusting for sex, age, hypertension, obesity, and interleukin (IL)-10, IL-4, and IL-6 levels." (PMID 36160136, 2022). "GSEA analysis showed that LINC01615 was associated with most of the immune pathways, such as the IL6 signaling pathway, IL1 and megakaryocytes in obesity, and the biocarta IL10 pathway." (PMID 35794984, 2022). "IL-6 is a pro-inflammatory cytokine, whose release in the bloodstream has been related to obesity and the development of type 2 diabetes." (PMID 36135761, 2022). "Obesity-associated inflammatory mediators, TNF-α, IL-6, together with glucocorticoids, stimulate the activity of PI.4, which subsequently increases the expression of aromatase." (PMID 35269622, 2022). "Obesity triggers inflammation marked by the secretion of low-grade inflammatory cytokines including interleukin-6, C-reactive protein, and tumor necrosis factor-α, leading to a condition known as “meta-inflammation”." (PMID 35740977, 2022).
Obesity (continued). "TNFα is a crucial cytokine in neuroinflammation secondary to obesity, even critical in glucose metabolism by attenuating insulin signaling pathways and increasing levels of IL6, activating a neuroinflammatory state." (PMID 35422689, 2022). "Regarding the effect of different training modalities on IL-6 levels in adolescents with obesity, there was homogeneity among studies (I2 = 0%, p = 0.59)." (PMID 36293806, 2022). "This nuclear factor modulates the expression of IL-6, TNF-α, and MIP; these cytokines are closely associated with obesity and pathogen responses." (PMID 35682832, 2022). "Although the plasma levels of IL-6 predict cardiovascular mortality, it has also been indicated that chronic IL-6 plasma predicts insulin resistance, obesity, and atherosclerosis." (PMID 36496428, 2022). "A similar modulatory action on IL-6, the major circulating inflammatory mediator in individuals with obesity, has been reported in preclinical studies." (PMID 36469320, 2022). "Last, BMI demonstrated a quite robust protective effect on OCD conditioned on CRP and IL-6 signaling, in accordance with observational data that OCD is associated with reduced odds of obesity." (PMID 35385317, 2022). "The levels of inflammatory cytokines related to the development of obesity, such as TNFα, IL-6, and MCP-1, were higher in the adipose tissues of Reg4 KO mice than in those of the control mice." (PMID 35074011, 2022). "Adipose tissue produces increased levels of inflammatory markers, including TNF-α and IL-6 in dietary manipulated obesity models." (PMID 36056976, 2022). "In obesity, accumulation of free fatty acids activates pro-inflammatory serine kinase cascades, which in turn promotes adipose tissue to release interleukin-6 that stimulates hepatocytes to synthesize and secrete CRP." (PMID 36235852, 2022). "Most patients with obesity exhibit increased circulating levels of inflammatory markers such as IL-6, IL-1, TNF and MCP1." (PMID 35842665, 2022). "For example, although related research is limited, a recent study further put forward that IL-6 is the mediation between obesity and OSA." (PMID 35967324, 2022). "In our study, obesity-induced damage to the heart was associated with NF-κB activation and increased in ICAM-1, PECAM-1, TNF-α, IL-1β, and IL-6 expression levels." (PMID 35625374, 2022). "Individuals living with obesity also had higher concentrations of IL-6 and leptin in comparison to normal weight individuals allocated to the corn oil intervention group." (PMID 35958557, 2022). "On the other hand, other studies have reported increased levels of IL-6 in subjects with obesity after HFM ingestion." (PMID 36258233, 2022). "A higher level of IL-6 level was observed in obesity conditions (OBOA) and it was reduced after treatment." (PMID 35354886, 2022). "Whereas in obesity-associated to T2DM, IL-6 as an inflammatory factor probably increases the existing inflammation." (PMID 35145895, 2022). "For example, in obesity, adipocyte-derived IL-6 promotes macrophage infiltration while myeloid-derived IL-6 suppresses it." (PMID 35477832, 2022). "Individuals with obesity have higher circulating lipopolysaccharide (LPS) levels associated with elevated pro-inflammatory cytokines TNF-α and IL-6 expression." (PMID 35579462, 2022). "Adipose secretome, including two of the most abundant and well-studied adipokines, leptin and interleukin-6, is involved in the regulation of energy metabolism and obesity-related low-grade inflammation." (PMID 35631195, 2022). "During obesity, adipose tissue produces cytokines such as IL1ß, IL6, IFNγ, TNFα, MCP1, promoting chronic inflammation." (PMID 35422689, 2022). "IL-6 is also one of the most important and abundant myokines released from skeletal muscle after exercise, and it has been shown to have anti-obesity and anti-inflammatory functions." (PMID 35909571, 2022).
Obesity (continued). "Patients with obesity produce higher levels of cytokines such as IL-6, C-reactive protein and TNF-α than normoweight individuals." (PMID 35955431, 2022). "Among them, we found that IL-6 and its related pathways play an important role in treating obesity through alleviating inflammation." (PMID 36105933, 2022). "Pro-inflammatory cytokines such as tumor necrosis-alpha (TNF-α), interleukin-1 (IL-1), and interleukin-6 (IL-6), which are increased in response to obesity, induce insulin resistance at a molecular level by modulating the insulin signaling pathway." (PMID 35883605, 2022). "Many proinflammatory cytokines such as TNFα and IL-6 are expressed under the induction of obesity or LPS." (PMID 36430282, 2022). "Consistent with the heightened activation of PRRs, ELISA showed that serum cytokine concentrations of TNF-α, IFN-γ, IL-1β, IL-6, and IL-17A were significantly induced with obesity, as was anti-inflammatory TGF-β and IL-10." (PMID 36406423, 2022). "Several studies have shown that mice fed an HF diet showed increased levels of inflammatory cytokines (Tnfα and Il6) in the ileum, colon, and surrounding mesenteric fat, even before the development of obesity." (PMID 35747264, 2022). "IL-6 was lower in lean women compared to women with obesity and women with obesity-diabetes at fasting and remained so at 2 h and 5 h post prandial (P = 0.003), with the level of IL-6 increasing over time particularly in the lean women and women with obesity." (PMID 35933445, 2022). "Free-choice-diet-induced obesity and NASH were also associated with elevated systemic inflammation, as reflected by higher serum MCP-1 and IL-6 levels." (PMID 36146875, 2022). "Myokines affecting sarcopenic obesity include IL-6, IL-10, IL-15, myostatin, insulin-like growth factor (IGF-1), irisin, FGF-21, and leukemia inhibitory factor (LIF)." (PMID 35250869, 2022). "The main mechanism by which obesity can cause vascular changes involves perivascular adipose tissue, which can secrete TNF-α and IL-6." (PMID 36013196, 2022). "Sankey plot analysis connected a total of 25 miRNAs that are known to be regulators of canonical inflammatory genes involved in obesity, such as TNF-α, IL-6, and IL-1β, to the list of L_Ag-associated DEMs and O_Ag-associated DEMs." (PMID 35798800, 2022). "For instance, promoted oxidative stress and suppressed immune system are linked with increases in inflammatory factors and adipokines (TNF, leptin, IL-1β, and IL-6) in obesity." (PMID 35628513, 2022). "Dysregulated adipocytokines and adipokines in obesity, such as leptin, resistin, TNF, and IL-6, are associated with the vascular dysfunction process." (PMID 35883829, 2022). "Nonetheless, obesity‐related dose of leptin elevated not only the release of IL‐6 and IL‐17, but also IL‐5 and IL‐13 by CD4+ T cells in lean‐derived cell cultures from patients." (PMID 35734271, 2022). "Interleukin-6 (IL-6) and oncostatin M, another member of the IL-6 family, both cytokines with established links to obesity and inflammatory disorders, are also potent activators of STAT3, and contribute to acute and chronic liver pathophysiology." (PMID 35162992, 2022). "The level of IL-6 increases significantly in adipose cells in obesity, which is due to the presence of inflammation." (PMID 35806019, 2022). "HOMA-IR negatively confounded the association (OR 1.88, 95% CI 0.63–5.59) and interleukin 6 positively confounded the association between TTV load and obesity (OR 5.82, 95% CI 1.76–19.22)." (PMID 36246898, 2022). "Dietary saturated fatty acids are deleterious to metabolic health and have been correlated to obesity, hepatic steatosis, type 2 diabetes, and systemic inflammation mediated by IL-6." (PMID 35204867, 2022). "In this case, altered IDO1 expression leads to Kyn accumulation, which enhances AhR/STAT3/IL-6 signaling in adipocytes to mediate obesity and insulin resistance." (PMID 35715443, 2022).
Obesity (continued). "High blood levels of the cytokine IL-6 occur in patients with obesity and in patients with hepatocarcinoma." (PMID 36038791, 2022). "Using IL-6R deficient and sIL-6R+/+ trans-signalling mice, we analysed the specific role of IL-6 classic and trans-signalling in diet-induced obesity and physical exercise." (PMID 36387898, 2022). "Many studies have found that the roles of inflammatory adipokines such as TNFα, IL6, and IL1β in obesity-related diseases are attributed to altered miRNA profiles." (PMID 36421371, 2022). "In our study, this inflammatory state was evidenced by the high plasma concentrations of TNF-α and IL-6 in untreated animals and even in those treated with a nutritionally adequate diet, in which obesity was induced for 17 weeks with HGLI diet." (PMID 36364929, 2022). "IL-6 and TNFα are cytokines that are widely used as indicators of the pro-inflammatory state that characterises obesity and contribute to insulin resistance." (PMID 35883817, 2022). "Weight gain and obesity often result in the increased secretion of inflammatory factors and chemokines, including tumor necrosis factor alpha (TNFα), interleukin 6 (IL6), and monocyte chemoattractant protein-1 (MCP-1)." (PMID 36501080, 2022). "On the contrary, plasmatic TNF-α and IL-6 levels decreased after aerobic exercise in children with obesity and overweight." (PMID 36364954, 2022). "Overproduction of interleukin-6 (IL-6) and interleukin-1β (IL-1β) is an important feature of obesity, which contributes significantly to IR." (PMID 35721805, 2022). "Whole-body IL-6 knockout mice develop mature onset obesity and an overall increase in fat mass, a phenotype partially reversed by injection of IL-6." (PMID 35054284, 2022). "Interleukin 6 and fasting insulin resistance were confounders of the association between TTV and obesity, while age was an effect modifier." (PMID 36246898, 2022). "IL-6 is a pro-inflammatory cytokine that is secreted by a variety of organs, including hepatocytes and adipose tissue; it has been reported that obesity and NAFLD are related to IL-6 hepatic overexpression." (PMID 36290594, 2022). "For example, in obesity, IL-6 acts as a Th2 cytokine by stimulating M2 polarization and local ATM proliferation, whereas Th1 cytokines such as TNF-α inhibit local ATM proliferation." (PMID 35468098, 2022). "More and more evidence is now emerging to suggest the role of IL-6 in the prevention of obesity and insulin resistance." (PMID 36358526, 2022). "Chronic low-grade inflammation characterized by higher levels of Il-1b and Il-6 has been reported to be one of the hallmarks of obesity-induced insulin resistance." (PMID 35967777, 2022). "The mRNA and protein levels of F4/80, MCP1, interleukin (IL)-1β, and IL-6 expressions were significantly upregulated by obesity in lung tissues." (PMID 36060644, 2022). "Plasma galectin-1 was suppressed by LPS treatment and obesity and IL-6−/− knockout modulated the response." (PMID 36295832, 2022). "TNF-α is related to the development of obesity-related insulin resistance, whereas IL-6 promotes lipolysis." (PMID 36304965, 2022). "Several recent studies demonstrated that the levels of inflammatory factors, such as TNF-α and IL-6, in patients with obesity and type 2 diabetes mellitus, are significantly higher than those in the control group and positively correlated with serum ASP." (PMID 35381008, 2022). "In contrast, the cerebrospinal level of IL-6 in humans is reported to be negatively correlated with obesity, and central IL-6 expression in obese rodents is reduced." (PMID 35470093, 2022). "Our study is the first to report on sexual dimorphism in IL-6 production during diet-induced obesity." (PMID 34439950, 2021). "AT also produces pro-inflammatory adipokines, and their expression is enhanced by obesity, such as leptin, TNFα, and interleukin-6 (IL-6)." (PMID 34836382, 2021).